MARCHF9 (membrane associated ring-CH-type finger 9)
Description:
E3 ubiquitin-protein ligase that may mediate ubiquitination of MHC-I, CD4 and ICAM1, and promote their subsequent endocytosis and sorting to lysosomes via multivesicular bodies. E3 ubiquitin ligases accept ubiquitin from an E2 ubiquitin-conjugating enzyme in the form of a thioester and then directly transfer the ubiquitin to targeted substrates.
Synonyms: MARCH-IX; MARCH9; RNF179; FLJ36578
Tractability: Antibody: UniProt predicts a signal peptide or a membrane-spanning region. PROTAC: ubiquitination databases record sites on it.
Gene: Protein-coding gene on chromosome 12 (57,755,103 to 57,760,411, forward strand). Ensembl gene ENSG00000139266.
Subcellular location: Golgi apparatus membrane; Lysosome membrane
Gene Ontology:
Molecular function: protein binding; ubiquitin-protein transferase activity; ubiquitin protein ligase activity; zinc ion binding
Biological process: protein ubiquitination
Cellular component: Golgi membrane; Golgi stack; lysosomal membrane; trans-Golgi network
Genetic constraint (gnomAD): Loss-of-function variants: 16 observed, 27.81 expected, observed/expected ratio (o/e) 0.58, 90% interval 0.39 to 0.87. The upper end of that interval is the gene's LOEUF score, 0.87, which puts it in group 3 of 6, group 1 being the genes least tolerant of losing a copy. Missense variants: 378 observed, 380.23 expected, observed/expected ratio (o/e) 0.99, 90% interval 0.91 to 1.08. Synonymous variants: 181 observed, 153.18 expected, observed/expected ratio (o/e) 1.18, 90% interval 1.05 to 1.34.
Homologues: Orthologues: chimpanzee MARCHF9 (99% identical), macaque MARCHF9 (99% identical), dog MARCHF9 (97% identical), pig MARCHF9 (97% identical), rat Marchf9 (96% identical), mouse Marchf9 (96% identical), guinea pig MARCHF9 (94% identical), tropical clawed frog marchf9 (75% identical), zebrafish marchf9 (72% identical). Paralogues in human: MARCHF4 (60% identical), MARCHF11 (45% identical), MARCHF1 (21% identical), MARCHF8 (20% identical), MARCHF3 (17% identical), MARCHF2 (16% identical).
Diseases named in the same sentence as MARCHF9 in open-access papers:
MARCHF9 is named in the same sentence as 14 diseases in open-access papers, as found by Europe PMC text mining. Sharing a sentence is not in itself a finding about the gene and the disease. The quoted sentences say what the papers report.
breast carcinoma (2 papers, 2021 to 2024). "This analysis, performed using an unpaired Student's t-test, revealed notable upregulation of MARCHF9 expression in multiple cancer types, including bladder and breast cancer." (PMID 39185021, 2024).
colorectal cancer (2 papers, 2022 to 2024). A primary or metastatic malignant neoplasm that affects the colon or rectum. "In this paper, we provide a comprehensive overview of colorectal cancer and highlight the significance of MARCHF9 in cellular processes." (PMID 39185021, 2024). "While our understanding of MARCHF9's functions in normal physiology has expanded, its role in carcinogenesis, particularly in colorectal cancer, remains poorly elucidated." (PMID 39185021, 2024). "The purpose of this study is to investigate the oncogenic role of MARCHF9 in colorectal cancer." (PMID 39185021, 2024). "In conclusion, our study illuminates the oncogenic role of MARCHF9 in colorectal cancer." (PMID 39185021, 2024).
lung adenocarcinoma (2 papers, 2017 to 2024). A carcinoma that arises from the lung and is characterized by the presence of malignant glandular epithelial cells. "Low MARCHF9 expression has been linked to poor prognosis and adverse clinicopathological characteristics of lung adenocarcinoma." (PMID 39185021, 2024). "Notably, MARCHF9 has been implicated in the prognosis of lung adenocarcinoma, where it suppresses tumor progression by downregulating ICAM-1." (PMID 39185021, 2024). "For instance, in lung adenocarcinoma, MARCHF9 overexpression has been correlated with favorable clinicopathological characteristics and can inhibit tumor invasion while showing little effect on cell proliferation." (PMID 39185021, 2024).
glioblastoma (1 paper, 2024). The most malignant astrocytic tumor (WHO grade IV). "In glioblastoma, MARCHF9 has been implicated in tumor immune microenvironment." (PMID 39185021, 2024). "In glioblastoma, MARCHF9 has been reported to be involved in suppressive immune microenvironments." (PMID 39185021, 2024).
tumor (5 papers, 2020 to 2025). "These clinicopathological associations suggest that MARCHF9 might play a pivotal role in promoting tumor progression and metastasis." (PMID 39185021, 2024).
cancer (4 papers, 2022 to 2025). A tumor composed of atypical neoplastic, often pleomorphic cells that invade other tissues. "MARCHF9's association with adverse clinicopathological features and its functional impact on cancer cell behavior underscore its significance in CRC progression." (PMID 39185021, 2024). "The distinct pattern of MARCHF9's association with poor survival outcomes across various cancers suggests its broad applicability as a prognostic marker." (PMID 39185021, 2024). "High MARCHF9 expression is associated with advanced disease stages, metastasis, and adverse prognosis, while in vitro experiments demonstrate its functional impact on cancer cell proliferation and invasion." (PMID 39185021, 2024). "Across pan-cancer samples, this analysis revealed a consistent upregulation of MARCHF9 expression in cancer tissues, emphasizing its potential as a candidate oncogene." (PMID 39185021, 2024). "The role of MARCHF9 in promoting cancer cell proliferation has been documented in other malignancies." (PMID 39185021, 2024). "To gain insights into the potential role of MARCHF9 in CRC and various other cancer types, we conducted a comprehensive analysis of MARCHF9 expression using data from the Cancer Genome Atlas (TCGA) cohort." (PMID 39185021, 2024). "To further refine our analysis, we performed a paired analysis to compare MARCHF9 expression in cancer tissues with their corresponding paired normal tissues." (PMID 39185021, 2024). "Initially, we observed significant variations in MARCHF9 mRNA levels in pan-cancer tissues compared to normal tissues." (PMID 39185021, 2024). "Strategies aimed at inhibiting MARCHF9 expression or activity could be explored to impede cancer cell proliferation and invasion." (PMID 39185021, 2024). "Similarly, when focusing on COAD and READ samples, the paired analysis highlighted a significant increase in MARCHF9 expression in cancer tissues relative to paired normal colorectal tissues." (PMID 39185021, 2024). "This upregulation aligns with findings in other cancer types, suggesting that MARCHF9 may serve as an oncogenic factor in multiple malignancies." (PMID 39185021, 2024). "In summary, while MARCHF9's clinical significance is widely recognized, its functional roles and mechanisms of action may vary depending on the specific cancer type." (PMID 39185021, 2024). "However, it is essential to acknowledge differences in MARCHF9's role across cancer types." (PMID 39185021, 2024). "This suggests that MARCHF9 may contribute to the invasive properties of COAD cells, further emphasizing its potential as a critical factor in cancer progression." (PMID 39185021, 2024).
MARCHF9 also shares sentences with these, for which no sentence is quoted: Obesity (2 papers); acute myeloid leukemia (1); adenocarcinoma (1); breast tumors (1); colorectal adenocarcinoma (1); encephalitis (1); lung squamous cell carcinoma (1); mucinous adenocarcinoma (1).